UHRF1 (ubiquitin like with PHD and ring finger domains 1)
Diseases named in the same sentence as UHRF1 in open-access papers (continued):
Sharing a sentence is not in itself a finding about the gene and the disease.
tumor (164 papers, 2003 to 2026). "The individual correlation of DNMT1, G9a and UHRF1 tumor expression with clinical-pathological variables revealed significant association with specific events, such as tumor stage or microvascular invasion." (PMID 39810240, 2025). "Other studies have also shown that mutations in DNA methylation machinery, such as DNMTs, TETs, and UHRF1, can also cause neoplasia." (PMID 40558829, 2025). "Malignant proliferation of tumor cells induced by gefitinib/osimertinib resistance were due to hypermethylation of the MUC17-specific promoter caused by the UHRF1/DNMT1 complex, which activates the NF-κB signaling pathway." (PMID 36778111, 2023). "Following the observation that UHRF1 loss appears to reduce tumor vascularization, we probed UHRF1 VC and KO orthotopic xenografts for the vasculature marker CD31." (PMID 36068209, 2022). "TAMs stimulated tumor UHRF1 expression and were positively associated with tumor UHRF1 expression in HCC." (PMID 35664070, 2022). "Having excluded cell proliferation and activation of the interferon pathway as potential mechanisms for tumor suppression by Uhrf1-TTD-KI mutation, we examined if elevated apoptosis occurred in Uhrf1ki/ki/ApcMin/+ mice." (PMID 33947834, 2021). "UHRF1 is also associated with epigenetic silencing of various tumor suppressors and other tumor-related genes, including CDKN2A, RB, BRCA1, RASSF1, PPARG, APC, CDH1, and RGS2." (PMID 31064417, 2019). "Up-regulated UHRF1 was broadly implicated in tumor progression, including cell proliferation, metastasis and chemoresistance." (PMID 31442209, 2019). "Tumor xenografts were established in immune-deficient nude mice by inoculating DU145-DR or UHRF1-depleted DU145-DR cells." (PMID 29752436, 2018). "Clinically, overexpression of UHRF1 in primary tumor tissues was significantly associated with poor survival and the prognostic high-risk 16-gene signature." (PMID 29507645, 2018). "On the contrary, another study showed an association between UHRF1 gene expression and tumor recurrence in superficial bladder cancer of Chinese cases." (PMID 28128913, 2017). "The tumor mass was dramatically greater in mice transplanted with UHRF1-deficient HepG2 cells compared with those that received the parental cells." (PMID 28584306, 2017). "In this current study, we further investigated the signaling mechanisms underlying the role of UHRF1 deficiency in EMT associated with tumor malignancy." (PMID 28584306, 2017). "In this regard, UHRF1-deficient HepG2 cells and their parental cells were engrafted into mice, and tumor formation was assessed." (PMID 28584306, 2017). "UHRF1 knockdown reduced in vitro proliferation, clonogenicity and anchorage-independent growth and caused reactivation of numerous tumour suppressor genes." (PMID 28587163, 2017). "Future studies are necessary to confirm our findings and to investigate potential mechanisms how global DNA hypomethylation caused by UHRF1 overexpression affects tumor progression." (PMID 27507047, 2016). "The association with UHRF1 activation, especially in advanced tumor stages, suggests that they are part of a more complex regulatory circuit." (PMID 22848209, 2012). "Investigating whether these molecules are epigenetically modulated through the miR-1–UHRF1 axis will be essential for elucidating the epigenetic mechanisms underlying tumor regulation mediated by miR-1 and UHRF1." (PMID 41373864, 2025). "First, we found that SIRT6-deficient tumor cells produced higher extracellular lactate levels than their control cells, which could be abolished with UHRF1-KD." (PMID 39709438, 2024). "Given that UHRF1 is required for SIRT6-deficient BLCA in driving tumor growth, we therefore questioned whether the UHRF1 specific inhibitor, NSC232003, could effectively suppress BLCA." (PMID 39709438, 2024).
tumor (continued). "Indeed, several studies show that epigenetic aberrations such as the loss of DNMT1 protein expression or DNMT1/PCNA/UHRF1 complex integrity are the source of genetic instability (deletion, translocation) and point mutations promoting tumor formation." (PMID 36278678, 2022). "UHRF1 is an important epigenetic regulator associated with apoptosis and tumour development." (PMID 32609811, 2020). "Our findings provide a novel mechanism that may explain how UHRF1 deficiency is positively associated with tumor malignancy." (PMID 28584306, 2017). "Univariate analysis showed that elevated UHRF1 mRNA and protein expression were prominently associated with clinicopathologic parameters such as tumor size, tumor differentiation, TNM stage, tumor microemboli, tumor metastasis, recurrence, and relapse-free survival time (P < 0.05)." (PMID 28060737, 2017). "UHRF1 overexpression relates to tumor stages, risk of recurrence and low survival rate." (PMID 28881702, 2017). "In conclusion, UHRF1 deficiency is closely correlated with tumor malignancy." (PMID 28584306, 2017). "However, positive expression of UHRF1 was associated with larger tumour size (>20 mm diameter, as measured in pathology; Fisher's exact test, p = 0.02)." (PMID 26497117, 2016). "Because UHRF1 was significantly overexpressed in the upper tract TCCs, UHRF1 might be a useful diagnostic marker especially for this type of tumour." (PMID 19491893, 2009). "Notably, chromatin regulators Hells and Uhrf1 were identified to be expressed in murine RB tumors, but their expression was abrogated in E2f1 or E2f3‐deficient background in the same murine RB model with a concomitant rescue of the tumor development phenotype." (PMID 32840881, 2021). "Overexpression of ubiquitin-like with PHD and RING Finger domains 1 (UHRF1) in a variety of haematological and tumors was noted beforehand, as well as a significant association of its remarkable expression with attenuated expression of a number of tumor susceptibility genes (TSGs)." (PMID 31428652, 2019). "Interestingly, high expression of 4 genes targeted by anti-tumor miRNAs was significantly associated with poor prognosis of patients with RCC according to TCGA database analyses (UHRF1: p = 4.87E-06, LOXL2: p = 0.0343, PLOD2: p = 0.000855 and SKA1: p = 1.44E-07)." (PMID 29928475, 2018). "The combination of UHRF1 knockdown with enzalutamide treatment demonstrated synergistic tumor inhibitory effects both in vitro and in vivo." (PMID 41760602, 2026). "Tumour suppressor genes that were previously suppressed by UHRF1 were restored following demethylation therapy." (PMID 40579780, 2025). "Overall, our findings suggest that UHRF1 methylates tumour suppressor genes to sustain the malignancy of T‐LBL." (PMID 40579780, 2025). "UHRF1 is essential for maintaining methylation patterns on newly synthesized DNA strands during the S phase of replication, thereby silencing tumor suppressor genes." (PMID 41373864, 2025). "UHRF1 suppresses the expression of tumor-suppressor genes by promoting methylation of their promoters." (PMID 41373864, 2025). "This process triggers the ubiquitination of UHRF1, resulting in the degradation of the DNMT1 protein, which in turn causes abnormal methylation of tumor suppressor gene promoters and promotes cancer development." (PMID 39981244, 2025). "In this study, we aimed to explore the roles of DNMT1, G9a, and UHRF1 proteins in this tumor by evaluating their expression in human PDAC tissue specimens." (PMID 39810240, 2025). "Of particular note, PLK1 and UHRF1 emerged as potential oncogenic hubs, reaffirming their roles in both tumour proliferation and ferroptotic resistance." (PMID 41007424, 2025). "In all tumors we examined, treatment with 5-Ph-IAA led to a complete degradation of the cognate target, and this result was further confirmed by performing immunohistochemistry (IHC) for UHRF1 on tumor sections." (PMID 40595593, 2025).
tumor (continued). "In conclusion, our study demonstrated the tumor-suppressive role of miR-1 and its ability to suppress UHRF1 expression in CCA." (PMID 41373864, 2025). "Silencing UHRF1 increased GSN expression, induced cell-cycle arrest, and promoted apoptosis, suggesting that GSN suppression via the USP7–UHRF1 axis supports tumor progression." (PMID 41148856, 2025). "This intricate interplay forms a positive transcriptional feedback loop between NKX2‐5/LHX1 and UHRF1, thus promoting the overexpression of all three genes and ultimately facilitating tumor growth." (PMID 40307990, 2025). "Lastly, MKI67, UHRF1, and ESPL1 are associated with tumor proliferation and epigenetic regulation, with UHRF1 contributing to DNA methylation and DDR‐related transcriptional control." (PMID 40405535, 2025). "Another report suggests that SIRT4 is a downstream target of UHRF1 (ubiquitin-like with plant homeodomain and ring finger domains 1), an epigenetic modifier known to mediate the silencing of tumor suppressor genes." (PMID 39682281, 2024). "The overexpression of UHRF1 repressed the transcription of such tumor-suppressor genes as CDKN2A, BRCA1, and CDH1 through DNMT1-mediated DNA methylation." (PMID 38725075, 2024). "In pancreatic cancer cells, UHRF1 overexpression promotes aerobic glycolysis and supports tumor growth and metastasis, in part by stabilizing HIF1α and enhancing the transcription of glycolytic genes." (PMID 39682281, 2024). "HE staining of the liver revealed that Stub1 and Uhrf1 increased the number of lesions in the tumor." (PMID 39267107, 2024). "Hence, YTHDF1 might cause changes in UHRF1 and Ki67 expression in tumour tissues." (PMID 38683130, 2024). "We show that SKF83566 suppress GBM progression and invasion via the DRD1-c-Myc-UHRF1 axis in vitro as well as in an orthotopic tumor model in mice." (PMID 38246990, 2024). "Then, we analyzed the TCGA-BLCA transcriptome data and found that UHRF1 expressions were aberrantly up-regulated in tumor samples relative to those in normal samples." (PMID 39709438, 2024). "UHRF1 promotes tumour progression by regulating proliferation, apoptosis, migration, invasion, and metastasis." (PMID 39046429, 2024). "Thymoquinone (TQ), a natural anticancer compound that induces the polyubiquitination of UHRF1, then triggers the apoptosis of tumor cells." (PMID 38725075, 2024). "Studies have shown that the upregulation of UHRF1 expression or enhanced function promotes the epigenetic silencing of tumor suppressor genes (TSGs), thereby facilitating tumor progression and drug resistance in tumors." (PMID 39267107, 2024). "UHRF1 overexpression epigenetically silenced the tumour suppressor genes in many various solid and haematological tumours." (PMID 38683130, 2024). "The western blots, tumorsphere formation assay, and 3D tumor spheroid invasion assay showed that UHRF1 over-expression led to enhanced tumor growth and invasion." (PMID 38246990, 2024). "The expression of UHRF1 was correlated with tumor necrosis, histological type and metastasis, and the differences were statistically significant (P = .013; P = .001; P = .002)." (PMID 38847665, 2024). "The aberrant expression of UHRF1 breaks the “epigenetic code”, leading to the silencing of tumor-suppressor genes (TSGs) through promoter hypermethylation, accumulation, or repressive histone marks." (PMID 37630248, 2023).
tumor (continued). "Several studies have shown that the downregulation of UHRF1 with natural compounds in tumor cells induces the reactivation of various TSGs, inhibits cell growth, and promotes apoptosis." (PMID 37630248, 2023). "Herein, we demonstrated that UHRF1 functions as an epigenetic regulator that reprograms CSCs toward differentiation and tumor suppression via GLI1/Hedgehog and Wnt signaling." (PMID 37380646, 2023). "UHRF1 deficiency almost completely inhibited Myc-driven HCC formation, as demonstrated by the reduced liver weight, liver to body weight ratios, and tumor numbers." (PMID 37380646, 2023). "This UKP cell line retained expression of Uhrf1 protein, again suggesting that tumor development in the UKP model is due to incomplete Cre-mediated deletion of UHRF1." (PMID 37407562, 2023). "Administration of hinokitiol, a potential UHRF1 inhibitor, significantly reduced tumor growth and CSC phenotypes in mice with Myc-driven HCC." (PMID 37380646, 2023). "Flow cytometry measurement of GFP:mCherry ratios in samples prior to implantation and at the end of study revealed that the knock-out of UHRF1 with two different sgRNAs leads to a significant decrease in tumor growth." (PMID 37407562, 2023). "Uhrf1 knockout strongly reduced tumor incidence and volume, whereas the livers of control mice were occupied by multiple tumors." (PMID 37380646, 2023). "In conclusion, our study suggests that PMA-induced differentiation of THP-1 cells is promoted by the depletion of UHRF1 or DNMT1 which also reduced in vivo tumor growth." (PMID 37573395, 2023). "In contrast, UHRF1 knockdown inhibits the proliferation, invasion, and growth of tumor xenografts and reverses global DNA hypomethylation." (PMID 37630248, 2023). "Hepatocyte-specific Uhrf1 knockout (Uhrf1HKO) strongly suppressed tumor initiation and CSC self-renewal in both diethylnitrosamine (DEN)/CCl4-induced and Myc-transgenic HCC mouse models." (PMID 37380646, 2023). "The high expression of UHRF1 inhibits a variety of tumor suppressor genes, such as BRCA1, KISS1, and MEG." (PMID 35656341, 2022). "It has been reported that UHRF1 silences tumor suppressor genes through recruiting epigenetic enzymes, including DNA methyltransferase (DNMT1) and histone lysine methyltransferases (G9a and Suv39H1) 10-13." (PMID 35664070, 2022). "We demonstrated that TAM-derived PGE2 stimulated tumor UHRF1 expression via blocking miR-520d expression, loss of miR-520d expression led HCC progression via tumor UHRF1, and tumor UHRF1 targeted tumor repressor KLF6." (PMID 35664070, 2022). "The expression level of UHRF1 was significantly increased in tumor cells, and the protein level of UHRF1 was generally increased at each stage of the cell cycle." (PMID 35211429, 2022). "Although KLF6 and CSF1 are differentially regulated by UHRF1, their regulatory mechanisms are functionally orchestrated to help UHRF1 fulfill its tumor-promoting roles in the course of HCC progression." (PMID 35664070, 2022). "UHRF1/DNMT1 also involve in promoter hypermethylation of tumor suppression genes (TSGs) to downregulate its expression and inhibits cellular apoptosis." (PMID 35951156, 2022). "More importantly, we need to explore the effects of UHRF1 on various tumors through mediating tumor immunity and DNA methylation." (PMID 35656341, 2022). "In this work, we answer these questions by showing that TAM-derived PGE2 controls tumor UHRF1 expression." (PMID 35664070, 2022). "Altogether, the data indicates that UHRF1 promotes tumor cell CSF1 production, which in turn assists macrophage tumor trafficking and activation." (PMID 35664070, 2022). "Arising from the observation that UHRF1 KO xenografts presented with reduced tumor vascularization, we identified a new role of UHRF1 in the induction of angiogenesis." (PMID 36068209, 2022). "In order to observe the effect of UHRF1 gene expression on tumor, we divided the samples into high and low groups according to gene expression." (PMID 35656341, 2022).
tumor (continued). "Tumor growth was significantly reduced in UHRF1 iKO tumors (average tumor volume 0.356 ± 0.201 cm3; n = 5) compared to iVC tumors (1.455 ± 0.865 cm3; P = 0.02; n = 5)." (PMID 36068209, 2022). "Among others, UHRF1 was identified as a potential critical regulator of tumor initiation and progression following RB pathway inactivation." (PMID 36068209, 2022). "To explore how macrophages induced tumor UHRF1 expression, we isolated and cultured TAMs from fresh human HCC tissues and collected TAM supernatants." (PMID 35664070, 2022). "Endogenous Tet1 proteins were able to precipitate Cul4A/B, VprBP and Uhrf1 in the tumor cell line MCF7, which showed higher levels of Tet1s." (PMID 36056023, 2022). "As expected, knockdown of tumor UHRF1 or macrophage depletion comparably slowed down tumor growth and enhanced mouse survival." (PMID 35664070, 2022). "In order to determine the relationship between UHRF1 gene expression and tumor immune neoantigens, we counted the number of neoantigens in each tumor sample." (PMID 35656341, 2022). "To further demonstrate the functional relevance of the interaction between macrophages and tumor UHRF1 in vivo, we inoculated shUHRF1-expressing H22 cells into BALB/c mice with or without macrophage depletion." (PMID 35664070, 2022). "We cultured HepG2 cells with these molecules and found that PGE2 was the most potent molecule to induce tumor cell UHRF1 transcript and protein expression." (PMID 35664070, 2022). "UHRF1 overexpression has also been strongly correlated with tumor aggressiveness and poor clinical outcomes." (PMID 36060265, 2022). "Consistent with a substantial reduction in tumor burden, the Uhrf1ki/ki/ApcMin/+ mice had a significantly prolonged lifespan than Uhrf1+/+/ApcMin/+ mice." (PMID 33947834, 2021). "In general, the expression of P3H2, COL10A1, and C5 in tumor tissues was significantly increased than that in normal tissues, and the expression of UHRF1, considered as a tumor suppressor gene, was higher in normal tissues than in tumor tissues." (PMID 33934516, 2021). "In RB, HELLS was initially identified along with UHRF1 as candidate genes contributing to tumor progression in murine RB models." (PMID 32840881, 2021). "UHRF1 is abnormally expressed in tumours and immune-related diseases and plays an important role in regulating gene expression and the biological functions of cells." (PMID 33568199, 2021). "Ubiquitin like with PHD and ring finger domains 1 (Uhrf1) is an epigenetic modifier which is highly expressed in many tumor cells." (PMID 33744855, 2021). "The mRNA levels of UHRF1 in NSCLC tumour tissues were significantly higher than that in healthy tissues, which was shown by meta‐analysis, and the pooled mean difference was 1.62 (1735 patients, 95% CI 1.13–2.12, Z = 6.46, P < .00001)." (PMID 32495469, 2020). "Of note, UHRF1 protein expression is much higher in primary MM tumor and MM cells compared to normal hPBMCs, and with an unfavorable prognosis in MM." (PMID 32213189, 2020). "When xenografted mice were treated with MS‐275, there was a significant reduction in tumor areas from UHRF1‐knockdown group in comparison with control‐knockdown counterparts." (PMID 31782885, 2020). "The expression level of UHRF1 was higher in the MM primary tumor and MM cells compared to normal hPBMCs." (PMID 32213189, 2020). "Both control and UHRF1 knockdown cell‐injected eyes showed intravitreal tumor growth, which was often accompanied by tumor cell invasion into anterior chamber and retina." (PMID 31782885, 2020). "UHRF1 is involved in multiple diseases through the regulation of methylation, especially in tumours where the dysregulation of UHRF1 is frequently observed." (PMID 32495469, 2020). "Further investigation on the detailed biological function of UHRF1 and the anti-tumor effects of berberine-based treatments in preclinical models of human MM should be carried out." (PMID 32213189, 2020).